INS (insulin)
Diseases named in the same sentence as INS in open-access papers (continued):
Sharing a sentence is not in itself a finding about the gene and the disease.
Insulin resistance (continued). "Compared to women with normal glucose tolerance, half of women with GDM have increased insulin resistance and a third have reduced insulin secretion." (PMID 39081793, 2024). "Values of insulin and Homeostatic Model Assessment for Insulin Resistance (HOMA-IR) progressively increased going from NFG to IFG and to DM." (PMID 39196799, 2024). "This condition is a result of insufficient insulin and the increase in chemicals that lead to insulin resistance, including glucagon, growth hormone, and catecholamines." (PMID 38674903, 2024). "Taken together, these findings point to a clear role for 4-MU in promoting insulin sensitivity and reducing insulin resistance." (PMID 39451245, 2024). "Insulin resistance is characterized by a diminished ability of cells to respond to insulin signaling, resulting in impaired glucose utilization and disrupted glucose metabolism." (PMID 38449844, 2024). "Insulin resistance, coupled with hyperglycemia and insufficient insulin, has been shown to raise APOC3 concentrations." (PMID 39684468, 2024). "Effects on fasting glucose and insulin, Homeostatic Model Assessment of Insulin Resistance (HOMA-IR), HbA1c, adiponectin, leptin, IL-6, TNF-α, and C-reactive protein (CRP) in exercise vs control groups were analyzed using random effects meta-analysis." (PMID 38253590, 2024). "Insulin resistance (IR) is characterized by decreased sensitivity of the body to insulin, resulting in abnormal glucose metabolism." (PMID 39588187, 2024). "Insulin resistance (IR) plays a pivotal role in hepatic steatosis development by rendering AT resistant to insulin’s antilipolytic effects, leading to increased release of free fatty acids (FFAs) that accumulate as TGs in the liver." (PMID 38539547, 2024). "Insulin resistance is clinically defined as the incapability of a known amount of insulin (endogenous or exogenous) to escalate glucose uptake and utilization in an individual similar to a usual one." (PMID 38672494, 2024). "In GD, the normal insulin signaling pathway is disrupted, leading to impaired glucose uptake and insulin resistance." (PMID 39519193, 2024). "The higher the proportion of adipose tissue in patients with a higher BMI, the stronger the insulin resistance and therefore insulin cannot develop any catabolic effects." (PMID 38773227, 2024). "Diagnosis performance determined by computational approach using the Matsuda index as reference for predicting insulin resistance (IR) in young men of surrogate indices, lipid indices, anthropometric measurement, serum glucose, and insulin levels." (PMID 38715798, 2024). "One of the main current treatments for type II diabetes and/or insulin resistance is metformin, which increases the insulin sensitivity of tissues by increasing GLUT4 expression." (PMID 39768255, 2024). "Insulin resistance (IR) is a medical condition that refers to a reduction in the responsiveness to insulin, promoting glucose uptake and utilization." (PMID 39345890, 2024). "The administration of HCQ to obese arthritic mice lowers insulin resistance, thus lowering the insulin levels and reducing weight." (PMID 39273629, 2024). "Existing studies have suggested a correlation between SJL and increased insulin resistance and insulin secretion, as well as elevated cortisol levels." (PMID 39300989, 2024). "Insulin resistance (IR) is a status in which the body’s tissues, including the brain, exhibit a low insulin response, leading to high levels of insulin in the blood." (PMID 38425702, 2024). "Insulin resistance (IR) underlies the pathogenesis of T2DM, reflecting reduced sensitivity of the body and tissues to insulin." (PMID 38622624, 2024). "ORs: odds ratios; CIs: confidence intervals; IR: insulin resistance; eIS: estimated insulin sensitivity." (PMID 38212850, 2024).
Insulin resistance (continued). "The intervention group demonstrated a marked reduction in serum lipopolysaccharide (LPS) levels and improved insulin sensitivity, as indicated by lower homeostatic model assessment of insulin resistance (HOMA-IR) scores." (PMID 39770729, 2024). "Both HOMA-IR and Matsudas insulin sensitivity index indicated increased insulin resistance in the HFD fed minipigs, an effect that was most pronounced in the OVX female minipigs based on the post hoc analysis." (PMID 38427692, 2024). "The calculation of insulin resistance using the insulin level of the individuals yields an index for insulin resistance named Homa-ir." (PMID 39765929, 2024). "Insulin resistance, characterized by a decrease in sensitivity or responsiveness to the metabolic actions of insulin, including insulin-mediated glucose disposal, has been widely identified as an independent risk factor for the development of CVD." (PMID 38715129, 2024). "Characterized as a metabolic disorder, type 2 diabetes mellitus is particularly notable for its features, including chronic inflammation, insulin resistance, and the gradual dysfunction of pancreatic β-cells responsible for insulin secretion." (PMID 39770517, 2024). "Impaired translocation of GLUT4 storage vesicles results in decreased insulin-stimulated glucose uptake, contributing to insulin resistance in both muscle and adipose tissues." (PMID 39125938, 2024). "Fasting glucose, insulin, homeostasis model assessment of insulin resistance, hemoglobin A1C, urea, and creatinine levels decreased, whereas uric acid levels increased (p < 0.05)." (PMID 39770995, 2024). "Insulin resistance is independently related to muscle weakness, whereas resistance exercise improves muscle insulin resistance, and low physical activity is an important risk factor considered for weight gain." (PMID 38540626, 2024). "Kef administration also improved insulin resistance; however, statistical significance was observed only 150 min after insulin injection." (PMID 39770698, 2024). "These cytokines, particularly in adipose tissue and the liver, contribute to insulin resistance by interfering with insulin signaling pathways." (PMID 39458444, 2024). "The hexosamine pathway is activated by elevated levels of glucose and insulin and is thought to contribute to the development of insulin resistance and type 2 diabetes." (PMID 38671903, 2024). "In terms of serum parameters, ICR mice showed an increase in glucose and insulin levels and consequently in the insulin resistance index." (PMID 39767584, 2024). "Note also that there are negative results in the prevention of insulin resistance: patients with diagnosed insulin resistance require insulin therapy." (PMID 38397072, 2024). "Recent studies have shown that miRNAs play essential roles in insulin synthesis and secretion, the regulation of β-cell function, and glucose metabolism, thus contributing to the development of insulin resistance and type 2 diabetes." (PMID 38805166, 2024). "Evidence from animal studies has confirmed that obesity can induce a condition known as insulin resistance, characterized by the cells’ inability to respond effectively to insulin." (PMID 38451930, 2024). "The leading cause of T2D is obesity-driven insulin resistance (IR) in the liver, skeletal muscle, and white adipose tissue (WAT), combined with impaired insulin secretion by pancreatic β-cells to overcome IR after a long period of over nutrition." (PMID 39191875, 2024). "Treatment of LD consists of two components, namely, to induce insulin secretion and to reduce insulin resistance." (PMID 39472276, 2024). "As documented in previous studies, chronic inflammation facilitates the development of T2DM by promoting insulin resistance and β-cell failure while decreasing insulin sensitivity." (PMID 39845886, 2024). "T3 also improves insulin sensitivity and glucose uptake in peripheral tissues, while T4 has a protective role against insulin resistance." (PMID 39203787, 2024).
Insulin resistance (continued). "Free fatty acids induce mitochondrial dysfunction and increase ROS production in skeletal muscle, which inhibits the insulin signaling pathway and reduces NO production, further contributing to insulin resistance." (PMID 39968366, 2024). "Studies have shown that similar to N-3 PUFAs, OA also can regulate metabolic diseases, owning to its anti-inflammatory and antioxidant properties, as well as effects on reducing DNA damage, promoting insulin secretion, and improving insulin resistance." (PMID 38501107, 2024). "In a model of non-alcoholic steatohepatitis, long-term use of beinaglutide reduced liver weight and hepatic steatosis and improved insulin sensitivity, and increased Sirt1 gene expression levels improved hepatic insulin resistance." (PMID 39598478, 2024). "Insulin resistance is a condition characterized by low peripheral tissue (muscle, liver, and adipose tissues) response to insulin." (PMID 38414818, 2024). "The deteriorated insulin resistance in B3galt5△IEC mice was further evidenced by elevated serum levels of insulin and leptin." (PMID 39004626, 2024). "The clinical studies further revealed that fenugreek reduced blood glucose and insulin resistance and enhanced insulin sensitivity." (PMID 39479631, 2024). "Fasting blood glucose (FBG) and insulin levels, homeostatic model assessment for insulin resistance (HOMA-IR), and semen analysis were assessed." (PMID 39055492, 2024). "Meanwhile, tangeretin also enhances insulin sensitivity, suggesting that it has the potential to improve insulin resistance, which is an important pathogenesis of metabolic diseases such as diabetes." (PMID 39682819, 2024). "For example, IFNα infusion has been shown to increase plasma insulin levels and delay insulin clearance, inducing insulin resistance in healthy individuals." (PMID 39768214, 2024). "PCOS is a multifaceted endocrine disorder frequently characterized by insulin resistance, resulting in elevated insulin concentrations within the circulatory system." (PMID 38195616, 2024). "Impaired insulin clearance and insulin resistance are germane to anti-tumor therapy because pharmacological inhibition of insulin-signaling (i.e., GLUT4 stimulation) decreases tumor glucose uptake, thereby limiting substrate availability for growth." (PMID 38166036, 2024). "Recent studies have suggested a potential link between AD and insulin resistance, which exhibits a decreased level of key insulin signaling proteins and an increased level of insulin resistance markers in the brains of AD mice." (PMID 39626951, 2024). "ω-3 PUFAs exert beneficial effects on metabolic control and insulin action, whereas depletion of ω-3 PUFAs contributes to the development of insulin resistance and inflammation with HFDs." (PMID 39201497, 2024). "This indicates that as a result of the use of an AIDiet in girls with PCOS, metabolic benefits related to improving insulin sensitivity and reducing insulin resistance typical of PCOS can be expected." (PMID 38347150, 2024). "The results obtained reveal the positive effects of EGCG on insulin resistance and show its potential to increase insulin sensitivity." (PMID 39770980, 2024). "Insulin resistance (IR) is a clinical condition characterized by impaired response of target tissues to insulin." (PMID 39192263, 2024). "Numerous research studies have highlighted the association between oxidative stress and the pathogenesis of insulin resistance, involving the inhibition of insulin signals and dysregulation of adipocytokines." (PMID 39081429, 2024). "Insulin resistance refers to a decrease in the sensitivity of peripheral tissues (primarily skeletal muscle, adipose tissue, and liver) to insulin, which is mainly characterized by impaired glucose uptake and utilization." (PMID 40302954, 2024).
Insulin resistance (continued). "Insulin resistance in poultry is characterized by elevated insulin levels post-fasting and high glucose levels, resulting in impaired liver fat and amino acid metabolism due to reduced glucose conversion." (PMID 39339244, 2024). "Type 2 diabetes (T2D) is a metabolic disorder that progresses continuously and is characterised by insulin resistance, often in conjunction with impaired insulin secretion." (PMID 39174611, 2024). "It was assumed that the enhancing effect of insulin on glucose fluctuations can be mitigated by insulin resistance." (PMID 39335526, 2024). "DM represents a group of physiological dysfunctions characterized by hyperglycemia due to insufficient insulin production, glucagon hypersecretion (type 1 DM), or directly from insulin resistance (type 2 DM)." (PMID 39057526, 2024). "Insulin resistance, characterized by decreased responsiveness to insulin, can have detrimental effects on skeletal muscle." (PMID 38302636, 2024). "Sympathetic activation leads to increased levels of catecholamines such as norepinephrine and epinephrine, inducing insulin resistance, inhibiting pancreatic insulin secretion, and resulting in elevated blood sugar." (PMID 38501097, 2024). "The Triglyceride-Glucose (TyG) index is a measure of insulin resistance that assesses the body's insulin sensitivity by combining two biomarkers, triglyceride and fasting blood glucose." (PMID 38184598, 2024). "These cytokines decrease glucose uptake by insulin-responsive tissues (peripheral insulin resistance) and stimulate pancreatic β-cells to release insulin." (PMID 38396558, 2024). "Postprandial glucose and insulin improved with 1 minute, and insulin resistance improved with 3 minutes, of SCD at a self-selected, comfortable pace, after consumption of a mixed meal in apparently healthy young adults." (PMID 38572086, 2024). "The assessment of insulin resistance using methods that rely on plasma insulin levels is invasive, expensive and difficult in large cohort studies, and not applicable in clinical screening." (PMID 38172828, 2024). "Insulin sensitizers, such as metformin and thiazolidinediones, are an important part of management of insulin resistance and can help in lowering insulin requirements." (PMID 39108603, 2024). "Previous studies demonstrated that apelin directly enhances insulin sensitivity and suggested that the circulating apelin elevations observed in insulin resistance states are compensatory." (PMID 37930396, 2024). "Hyperglycemia is another critical pathological feature of MS that is characterized by elevated blood glucose levels resulting from insufficient insulin secretion or insulin resistance (IR)." (PMID 39852511, 2024). "The relationship of AGEs to insulin sensitivity has been previously reported, while an excessive ingestion of dietary AGEs promotes insulin resistance in mice." (PMID 39518960, 2024). "Insulin resistance markers decreased while insulin sensitivity markers increased between the two time points." (PMID 38341196, 2024). "Insulin secretion decreases with age, insulin resistance increases with weight gain, and TG and HbA1c levels exhibited corresponding differences according to age and body size in the present study." (PMID 38391840, 2024). "HIF-P4H-2-deficient mice have improved glucose tolerance and insulin sensitivity, and oral administration of HIF-P4H inhibitor to wild-type mice improves insulin resistance and glucose intolerance during a high-fat diet." (PMID 38814443, 2024). "High-BCAA chow feeding did not alter food intake, water intake, fasting blood glucose levels, and insulin resistance, as detected by glucose tolerance tests and insulin tolerance tests in both STZ/HFD and db/db mice, compared with normal chow-fed mice." (PMID 39659577, 2024). "In another study, prolonged consumption of an HFD resulted in heightened levels of insulin in the serum, triggered insulin resistance, and promoted increased fat accumulation within the liver." (PMID 38542720, 2024).
Insulin resistance (continued). "LGAs conceived through ART were shown to have higher BMI, blood pressure, fasting blood glucose, fasting insulin, and homeostatic model assessment of insulin resistance values, even after controlling for all covariates." (PMID 38764021, 2024). "Skeletal muscle inflammation impairs insulin signaling and promotes the development of insulin resistance." (PMID 39107476, 2024). "In insulin resistance, beta cells increase insulin secretion to compensate for the hypertrophy of the pancreas and an increase in mass." (PMID 38822155, 2024). "In an animal model, vaspin level is significantly higher in obese mice with insulin resistance similar to our study group of mothers with GDM insulin-treated." (PMID 39795898, 2024). "In a recent international consensus published in Nature Medicine, T2DM is defined as “a disease characterized by the gradual decline of β cell insulin secretion function, often accompanied by excessive obesity and insulin resistance”." (PMID 39873003, 2024). "Adults with insulin resistance often exhibit reduced insulin production, poor glucose tolerance, and low blood and intracellular magnesium concentrations." (PMID 39429362, 2024). "Pioglitazone is a thiazolidinedione drug that selectively agonizes the peroxisome growth factor-activated receptor PPARγ, which enhances insulin sensitivity in peripheral tissues and the liver and reduces insulin resistance." (PMID 39598478, 2024). "Insulin resistance (IR) denotes a diminished response to insulin regulation, reflecting disrupted insulin and glucose metabolism." (PMID 38173012, 2024). "It is a group of metabolic diseases defined by abnormal insulin secretion or insulin resistance, resulting in persistent hyperglycemia." (PMID 39063971, 2024). "It is known that fasting glucose, insulin, and insulin resistance physiologically decrease during growth from mid-adolescence to young adulthood, and the vascular protective effect of this natural decline has been reported." (PMID 38173399, 2024). "From the second trimester, increased fat stores and placental hormones—such as estrogen, progesterone, leptin, and cortisol—reduce insulin sensitivity, leading to a natural increase in insulin resistance." (PMID 39770967, 2024). "There are different mechanisms in the pathophysiology of MetS, including adipose tissue remodeling due to obesity, hyperglycemia, insulin resistance, impaired insulin production, and hypertension." (PMID 38892574, 2024). "Apart from direct interpretation of glucose and insulin concentrations at particular time points of OGTT, some indices of insulin sensitivity (IS)/insulin resistance (IR) were introduced." (PMID 39125447, 2024). "Studies testing insulin resistance using the TyG index have demonstrated that it is superior to the HOMA-IR index due to its insulin independence." (PMID 39459383, 2024). "Here, we use C-peptide, which is more stable than insulin, to accurately assess β-cells function, and use DI, a marker of insulin resistance corrected, to explore the relationship between HUA and β-cells function." (PMID 38172728, 2024). "Accordingly, a decreased responsiveness of the sebaceous glands to insulin-mediated signals, i.e., (insulin resistance), is compensated by the upregulation of IGF-1, which stimulates the production of androgens." (PMID 39744637, 2024). "Type 2 diabetes primarily stems from insulin resistance and progressive deterioration of insulin secretion." (PMID 39149550, 2024). "IL-6 interferes with insulin signaling, contributing to insulin resistance and metabolic disorders related to glucose and lipid metabolism." (PMID 39691364, 2024). "Elevated FFA promote insulin resistance, inhibiting the insulin signaling pathway PI3K/Akt, which leads to a reduction in NO production regulated by this pathway." (PMID 39713052, 2024).